RUVBL1 (RuvB like AAA ATPase 1)
Description:
Possesses single-stranded DNA-stimulated ATPase and ATP-dependent DNA helicase (3' to 5') activity; hexamerization is thought to be critical for ATP hydrolysis and adjacent subunits in the ring-like structure contribute to the ATPase activity. Component of the NuA4 histone acetyltransferase complex which is involved in transcriptional activation of select genes principally by acetylation of nucleosomal histones H4 and H2A. This modification may both alter nucleosome-DNA interactions and promote interaction of the modified histones with other proteins which positively regulate transcription. This complex may be required for the activation of transcriptional programs associated with oncogene and proto-oncogene mediated growth induction, tumor suppressor mediated growth arrest and replicative senescence, apoptosis, and DNA repair. The NuA4 complex ATPase and helicase activities seem to be, at least in part, contributed by the association of RUVBL1 and RUVBL2 with EP400. NuA4 may also play a direct role in DNA repair when recruited to sites of DNA damage. Component of a SWR1-like complex that specifically mediates the removal of histone H2A.Z/H2AZ1 from the nucleosome. Proposed core component of the chromatin remodeling INO80 complex which exhibits DNA- and nucleosome-activated ATPase activity and catalyzes ATP-dependent nucleosome sliding. Plays an essential role in oncogenic transformation by MYC and also modulates transcriptional activation by the LEF1/TCF1-CTNNB1 complex. Essential for cell proliferation. May be able to bind plasminogen at cell surface and enhance plasminogen activation.
Synonyms: ECP-54; NMP 238; INO80H; NMP238; TIP49; TIP49A; RVB1; Pontin52; ECP54; TIH1; PONTIN
Tractability: Small molecule: a structure with a bound ligand is known; it has a high-quality binding pocket. PROTAC: UniProt records ubiquitination sites on it; ubiquitination databases record sites on it; its protein half-life has been measured; a small molecule that binds it is known.
Target class: Enzyme
Gene: Protein-coding gene on chromosome 3 (128,064,778 to 128,153,914, reverse strand). Ensembl gene ENSG00000175792.
Subcellular location: Nucleus matrix; Nucleus, nucleoplasm; Cytoplasm; Membrane; Cytoplasm, cytoskeleton, microtubule organizing center, centrosome; Dynein axonemal particle
Subcellular location (Human Protein Atlas): Nuclear speckles; Nucleoplasm; Basal body; Cytosol
Pathways (Reactome):
Cell Cycle: Deposition of new CENPA-containing nucleosomes at the centromere; Telomere Extension By Telomerase
Metabolism of proteins: UCH proteinases; Ub-specific processing proteases
Chromatin organization: HATs acetylate histones
DNA Repair: DNA Damage Recognition in GG-NER
Signal Transduction: Formation of the beta-catenin:TCF transactivating complex
Gene Ontology:
Molecular function: ATP hydrolysis activity; cadherin binding; DNA helicase activity; protein binding; TBP-class protein binding; transcription coactivator activity; ADP binding; ATP binding; ATP-dependent activity, acting on DNA; ATPase binding; TFIID-class transcription factor complex binding
Biological process: chromatin remodeling; positive regulation of canonical Wnt signaling pathway; positive regulation of DNA-templated transcription; positive regulation of double-strand break repair via homologous recombination; regulation of cell cycle; regulation of chromosome organization; regulation of DNA replication; regulation of DNA strand elongation; telomerase RNA localization to Cajal body; box C/D snoRNP assembly; protein stabilization; regulation of apoptotic process; regulation of DNA-templated transcription; regulation of double-strand break repair; regulation of transcription by RNA polymerase II; spermatogenesis; positive regulation of DNA repair; positive regulation of telomere maintenance in response to DNA damage; regulation of DNA repair; regulation of embryonic development; telomere maintenance
Cellular component: ciliary basal body; cytoplasm; cytosol; extracellular exosome; Ino80 complex; membrane; MLL1 complex; NuA4 histone acetyltransferase complex; nuclear speck; nucleoplasm; nucleosome; nucleus; protein folding chaperone complex; R2TP complex; RPAP3/R2TP/prefoldin-like complex; Swr1 complex; dynein axonemal particle; centrosome; nuclear matrix; ribonucleoprotein complex
Genetic constraint (gnomAD): Loss-of-function variants: 3 observed, 45.95 expected, observed/expected ratio (o/e) 0.0653, 90% interval 0.029 to 0.17. The upper end of that interval is the gene's LOEUF score, 0.17, which puts it in group 1 of 6, group 1 being the genes least tolerant of losing a copy. Missense variants: 291 observed, 579.3 expected, observed/expected ratio (o/e) 0.5, 90% interval 0.46 to 0.55. Synonymous variants: 214 observed, 220.1 expected, observed/expected ratio (o/e) 0.97, 90% interval 0.87 to 1.09.
Homologues: Orthologues: chimpanzee RUVBL1 (100% identical), dog RUVBL1 (100% identical), macaque RUVBL1 (100% identical), rabbit RUVBL1 (100% identical), mouse Ruvbl1 (99% identical), rat Ruvbl1 (99% identical), guinea pig RUVBL1 (99% identical), pig RUVBL1 (98% identical), rat Ruvbl1-ps1 (93% identical), zebrafish ruvbl1 (92% identical), tropical clawed frog ruvbl1 (86% identical), Drosophila melanogaster pont (79% identical). Paralogues in human: RUVBL2 (43% identical).
Diseases named in the same sentence as RUVBL1 in open-access papers:
RUVBL1 is named in the same sentence as 62 diseases in open-access papers, as found by Europe PMC text mining. Sharing a sentence is not in itself a finding about the gene and the disease. The quoted sentences say what the papers report.
lung cancer (8 papers, 2013 to 2024). A malignant neoplasm involving the lung. "High expression of RuvBL1 inversely with low c-Jun in lung cancer was associated with a poor overall prognosis." (PMID 34164343, 2021). "In particular, several studies suggested a potential use of RuvBL1 as a biomarker for diagnosis and prognosis of lung cancer." (PMID 34164343, 2021). "To investigate the clinical relevance of RuvBL1 and c-Jun in lung cancer, we analyzed their expression correlation by Oncomine analysis." (PMID 34164343, 2021). "In our study, RuvBL1 was highly expressed in TRAIL-resistance lung cancer cells compared to TRAIL-sensitive cells." (PMID 34164343, 2021). "Taken together, our studies broaden the molecular mechanisms of TRAIL resistance and suggest the application of silencing RuvBL1 synergized with TRAIL to be a novel therapeutic strategy in lung cancer treatment." (PMID 34164343, 2021). "Here, we report that RuvBL1 is highly expressed in lung cancer and promotes the resistance to TRAIL." (PMID 34164343, 2021). "Overexpression of RUVBL1 was also reported in hepatocellular carcinoma, colorectal tumor, nonsmall cell lung cancer, B-cell lymphoma, and breast cancer." (PMID 24396308, 2013). "RUVBL1 has been reported to promote the invasion of breast and pancreatic cancers and increased proliferation and resistance in various solid tumours, including lung cancer and colorectal cancers." (PMID 39402324, 2024). "RUVBL1/2 ATPase activity is increased in patients with non-small cell lung cancer, and the activity drives PAQosome maturation, DNA replication and radioresistance in lung cancer." (PMID 38609375, 2024). "These discoveries are consistent with previous studies, which also noted the elevated expression of RUVBL1 in other cancer types, such as oral squamous cell carcinoma, osteosarcoma, salivary gland cancer, lung cancer, hepatocellular carcinoma, colorectal carcinoma, and glioma." (PMID 38610951, 2024). "In addition, the expression pattern of high RuvBL1 and low c-Jun was associated with a worse survival in lung adenocarcinoma, as reported that RuvBL1 is a potential prognosis biomarker in lung cancer." (PMID 34164343, 2021). "Therefore, the clinical relevance of RuvBL1 and c-Jun in lung cancer supports our results that RuvBL1 overexpression maintains TRAIL resistance by downregulating c-Jun." (PMID 34164343, 2021). "Therefore, we speculate that RuvBL1 overexpression might be associated with TRAIL-resistance in NSCLC, and downregulation of RuvBL1 probably sensitizes lung cancer cells to TRAIL-induced apoptosis." (PMID 34164343, 2021). "For example, it can accelerate the progression of lung cancer by activating the RAF/MEK/ERK pathway, and the high expression of RUVBL1 in mammary carcinoma suggests a worse prognosis." (PMID 37362244, 2023). "The present study aimed to investigate expression levels and prognostic significance of RUVBL1 and HNRNPU in stage I and II non–small-cell lung cancer (NSCLC) patients." (PMID 36242708, 2022). "RUVBL1, a novel C-RAF-binding protein, was found to promote lung cancer tumorigenesis through the activation of the RAF/MEK/ERK pathway." (PMID 35512017, 2022). "Downregulation of RuvBL1 sensitized cells to TRAIL-induced apoptosis, and improved the efficacy of TRAIL in TRAIL-resistant lung cancer cells." (PMID 34164343, 2021). "In this study, we identified RuvBL1 as a repressor of c-Jun/AP-1 activity, contributing to TRAIL resistance in lung cancer cells." (PMID 34164343, 2021). "Most importantly, there is a negative correlation expression between RuvBL1 and c-Jun in lung cancer tissues, supporting our conclusion that RuvBL1 is a negative regulator of c-Jun." (PMID 34164343, 2021).
osteosarcoma (7 papers, 2015 to 2025). A usually aggressive malignant bone-forming mesenchymal neoplasm, predominantly affecting adolescents and young adults. "RUVBL1 can be regulated by CircMYO10/miR-370-3p in osteosarcoma and influences osteosarcoma progression." (PMID 37197432, 2023). "CircMYO10 promotes osteosarcoma progression by regulating miR-370-3p/RUVBL1 axis to promote chromatin remodeling and thus enhances the transcriptional activity of β-catenin/LEF1 complex, which indicates that circMYO10 may be a potential therapeutic target for osteosarcoma treatment." (PMID 31665067, 2019). "Moreover, we also found that circMYO10 promotes osteosarcoma progression by acting as a sponge for miR-370-3p to inhibit its anti-tumor effect, and upregulates the expression of its target gene, RUVBL1, which promotes histone H4 acetylation at the promoter region of C-myc." (PMID 31665067, 2019). "Our results show that RUVBL1 ATPase is essential for the growth of U2OS cells, which originate from an osteosarcoma." (PMID 26201077, 2015). "Molecularly, RUVBL1 enhances the transcriptional activity of the β-catenin/LEF1 complex by mediating chromatin remodeling at the promoter regions of LEF1 target genes, consequently promoting osteosarcoma metastasis." (PMID 37197432, 2023).
breast carcinoma (6 papers, 2013 to 2025). "The results showed that overexpression of RUVBL2 was associated with survival in breast cancer patients and that overexpression of RUVBL1 was associated with survival in liver cancer and cervical squamous cell carcinoma patients." (PMID 36171202, 2022). "To further clarify the mechanism by which RUVBL1 promotes resistance to radiation therapy in breast cancer cells, we used CoIP and mass spectrometry to search for proteins to which RUVBL1 potentially binds." (PMID 38609375, 2024). "In order to further explore how ubiquitination of RUVBL1 by DTL regulates the radiation resistance of breast cancer cells, we then performed transcriptomic analysis (RNA-seq) on radiation-irradiated breast cancer cells stably overexpressing RUVBL1." (PMID 38609375, 2024). "Previous studies have shown that RUVBL1 regulates tumor drug resistance and is involved in regulating the HR repair pathway in DNA damage, but its function in breast cancer radiation resistance is poorly understood." (PMID 38609375, 2024). "Subsequently, in vitro and in vivo experiments showed that RUVBL1 regulates the resistance of breast cancer cells to radiation therapy." (PMID 38609375, 2024). "To further understand the role of RUVBL1 and DTL in the regulation of breast cancer radiation resistance, we knocked down DTL in RUVBL1-overexpressing MDA-MB-231 cells to analyze the resistance of breast cancer to radiation therapy." (PMID 38609375, 2024). "Our findings suggest that RUVBL1 enhances DNA damage repair and radioresistance in breast cancer cells both in vitro and in vivo." (PMID 38609375, 2024). "Knockdown of β-catenin in breast cancer cells overexpressing RUVBL1 and DTL significantly reduced the expression level of NHEJ molecules." (PMID 38609375, 2024). "In this study, we found that ubiquitination of RUVBL1 by DTL enhances the radiation resistance of breast cancer cells." (PMID 38609375, 2024). "Knockdown of β-catenin significantly reduced RUVBL1-DTL-mediated radiation resistance of breast cancer in vitro and in vivo." (PMID 38609375, 2024). "The results indicate that DTL plays a crucial role in the radiation tolerance of breast cancer cells by ubiquitinating RUVBL1 at the K63 site." (PMID 38609375, 2024). "To further clarify the role of RUVBL1 in breast cancer radiation resistance, we constructed cell lines stably overexpressing or knocking down RUVBL1 in breast cancer cells (MAD-MB-231, MCF7 and BT549)." (PMID 38609375, 2024). "In this study, we used protein profiling to analyze a spontaneous model of irradiated mouse breast cancer and found that the expression level of RUVBL1 is clearly increased after irradiation." (PMID 38609375, 2024). "Subsequent studies in radiation-treated or untreated mouse mammary tumor tissues also confirmed that RUVBL1 was highly expressed in the radiation-treated group." (PMID 38609375, 2024). "RUVBL1 and YY1 promote tumor growth, and inhibiting RUVBL1 expression in metastatic breast cancer cells can reduce both cell proliferation and invasion." (PMID 38020889, 2023). "To further investigate whether RUVBL1 play a role in the resistance of breast cancer cells to radiotherapy, we have constructed MDA-MB-231 radioresistant cell lines (MDA-MB-231 RR)." (PMID 38609375, 2024). "Finally, breast cancer cells overexpressing RUVBL1 were inoculated into nude mice, and irradiated continuously after 12 days of tumor growth." (PMID 38609375, 2024). "In this study, we found that RUVBL1 interacts with DTL in radiation-irradiated breast cancer cells." (PMID 38609375, 2024). "This indicates that RUVBL1 plays a significant role in the radiation tolerance of breast cancer." (PMID 38609375, 2024). "Furthermore, we also detected the level of DNA damage in breast cancer cells overexpressing RUVBL1 after radiation treatment, and the results showed that overexpressing RUVBL1 significantly reduced the expression level of γ-H2AX protein in breast cancer cells." (PMID 38609375, 2024).
breast carcinoma (continued). "Therefore, we speculated that DTL may be involved in the regulation of RUVBL1 on the radiation resistance of breast cancer cells." (PMID 38609375, 2024). "Subsequently, it was discovered that the overexpression of RUVBL1/DTL greatly increased the expression of NHEJ repair pathway molecules, namely K70, K80, DNA-PKcs, 53BP1, LIG4, and XRCC4, within breast cancer cells." (PMID 38609375, 2024). "In this study, we elucidated that ubiquitination of RUVBL1 by DTL promotes the formation of RUVBL1/2-β-catenin complex, which in turn promotes the NHEJ repair pathway of breast cancer cells to resist radiation therapy." (PMID 38609375, 2024). "However, we found that DTL-ubiquitinated-RUVBL1 attenuates the interaction between RUVBL1 and TIP60, thereby reducing the acetylation level of H4K16 in breast cancer cells." (PMID 38609375, 2024). "Considering that RUVBL1 is ubiquitinated by DTL in breast cancer cells, we assumed that DTL might exert a radioresistance effect in breast cancer." (PMID 38609375, 2024). "Our results suggested that DTL ubiquitination of RUVBL1 promotes the formation of RUVBL1/2-β-catenin complex, thereby regulating the transcription of NHEJ repair pathway molecules and enhancing the resistance of breast cancer cells to radiation therapy." (PMID 38609375, 2024).
colorectal cancer (6 papers, 2022 to 2025). A primary or metastatic malignant neoplasm that affects the colon or rectum. "The upregulation and nuclear localization of RUVBL1 along with β-catenin are highly correlated with colorectal carcinoma progression, which enhances TCF/β-catenin-mediated transcription of Wnt target genes and may thus promote carcinogenesis." (PMID 35493294, 2022).
hepatocellular carcinoma (6 papers, 2012 to 2026). A malignant tumor that arises from hepatocytes. "In agreement with our studies, high expression of RUVBL1 was also shown in a variety of human solid tumors, such as colorectal, hilar cholangiocarcinoma, renal cell carcinoma, and hepatocellular carcinoma." (PMID 36242708, 2022). "However, a recent study found that a decrease in RUVBL1 promoted the progression of hepatocellular carcinoma." (PMID 37362244, 2023). "The question remains whether RUVBL1 at an increased level is involved in promotion of tumorigenicity in CEM T-lymphoblastic cells similarly as described in the study on human hepatocellular carcinoma." (PMID 23443080, 2012). "RUVBL1 overexpression correlates with poor survival in patients with hepatocellular carcinoma (HCC)." (PMID 42002035, 2026).
non-small cell lung carcinoma (6 papers, 2021 to 2024). A group of at least three distinct histological types of lung cancer, including non-small cell squamous cell carcinoma, adenocarcinoma, and large cell carcinoma. "Largely in agreement with our finding, highly expressed RUVBL1 in non-small cell lung cancer has been reported to be indicative of undesirable oncogenic outcomes of patients, serving as a promising prognostic biomarker." (PMID 37076452, 2023). "Non-small-cell lung cancer (NSCLC) patients with poor survival outcomes also had higher RUVBL1 and RUVBL2 expression in NSCLC." (PMID 35493294, 2022).